AHR (aryl hydrocarbon receptor)
Diseases named in the same sentence as AHR in open-access papers (continued):
Sharing a sentence is not in itself a finding about the gene and the disease.
autoimmune disease (continued). "Our findings suggest that inhibitors of GLK or the AhR-RORγt complex could be used as IL-17A–blocking agents for IL-17A–mediated autoimmune diseases." (PMID 30214937, 2018). "Th17 cell differentiation subsequent to ligand-dependent activation of AHR has also been observed in other models of autoimmune diseases, which may lead to exacerbation of inflammation involving neutrophilia." (PMID 29724254, 2018). "AhR plays an important role in the cellular metabolism of xenobiotics, and AhR signaling is considered as a promising drug target, particularly for cancer, inflammation, and autoimmune diseases." (PMID 26457112, 2015). "Therefore, our findings have not only advanced our understanding on AHR physiological function but also provided significant insight into the pathogenesis of degenerative disorders or autoimmune diseases including vitiligo." (PMID 26370050, 2015). "These Foxp3+ Tregs emerge over several days or weeks in different autoimmune disease models and may develop indirectly via AhR-dependent induction of tolerogenic dendritic cells." (PMID 24586378, 2014). "Further studies are needed to show whether modulation of the AhR pathways may offer a possible novel therapeutic approach for BD and other autoimmune diseases which are mediated by an aberrant Th1 and Th17 immune response." (PMID 25045206, 2014). "Depending on the presence of specific ligands, AHR activation may suppress or exacerbate experimental autoimmune diseases." (PMID 25400638, 2014). "More interestingly, the interaction between IDO1 and AhR may have important roles in the context of autoimmune diseases." (PMID 25566253, 2014). "Therefore, it will be interesting to examine the expression of AHR and AHR-related genes in dioxin-affected people with the aim of identifying the potential link between AHR induction and dioxin-related autoimmune diseases." (PMID 25400638, 2014). "The important role of the AHR and effects of AHR agonists or antagonists have been documented for various inflammatory conditions, stem cell stability and expansion, autoimmune diseases, and several different cancers and clearly demonstrate that this receptor is an important drug target." (PMID 25011475, 2014). "The fact that AhR activation leads to suppression of inflammation has been used recently to demonstrate its efficacy against some experimental models of inflammation and autoimmune disease." (PMID 21858153, 2011). "Additionally, the plant-derived compound resveratrol can inhibit AhR activity by blocking the binding of AhR with its ligands, potentially reversing the imbalance of Th17/Treg cells in patients with autoimmune diseases and showing therapeutic potential for AhR-mediated diseases." (PMID 39944639, 2025). "We thus propose a protective role for AhR–mast-cell activation driven by the microbiome, whereby natural metabolites or postbiotics will have a physiological role in immune homeostasis and may act as therapeutic targets in autoimmune diseases." (PMID 38509264, 2024). "In this review, we focus on the mechanisms through which Trp metabolism converges to AHR activation for the modulation of immune function and restoration of tissue homeostasis and how these processes can be targeted using therapeutic approaches for cancer and inflammatory and autoimmune diseases." (PMID 37394584, 2023). "Proper regulation of AHR-mediated signal transduction might be critical for maintaining immune cell function in autoimmunity, while abnormal AHR signaling has been closely related to the pathogenesis of autoimmune diseases." (PMID 35309329, 2022). "Thus, this review highlights how the discovery of AhR in the field of immunotoxicology contributed towards better understanding of this transcription factor and its potential use in regulating inflammatory and autoimmune diseases." (PMID 33105907, 2020).
autoimmune disease (continued). "AhR regulates the differentiation of Th17 and Treg cells, therefore, the difference in its expression shifts the balance between these two T cell subtypes and may contribute to their pathogenesis of autoimmune diseases." (PMID 32899152, 2020). "In addition, finding novel AhR agonists may be a logical next step to developing more effective probiotics to alleviate autoimmune diseases." (PMID 31772949, 2019). "However, there are very few studies on the role of AHR in PM-mediated autoimmune disease." (PMID 30574142, 2018). "In the context of autoimmunity, activation of AHR by exogenous and endogenous ligands modulates T cell differentiation as well as effector and regulatory T cell function, and contributes to antigen presenting cell responses, all of which alter autoimmune diseases." (PMID 30574142, 2018). "However, the possible role of AHR in dioxin-exposed people is still unknown, particularly in autoimmune disorders." (PMID 25400638, 2014). "At the same time, accumulating data from recent studies have shown that aryl hydrocarbon receptor (Ahr), plays a key role in regulating the differentiation of T cell subsets, especially Th17 and Treg cells, and consequently affects the development of several autoimmune diseases including RA." (PMID 24905409, 2014). "Previous studies have demonstrated that activation of AhR by specific ligands regulates the generation of regulatory T cells, modulates the Th1 and Th2 balance, and increases the proportion of Th17 cells and their production of cytokines to promote the development of autoimmune diseases." (PMID 24905409, 2014). "It was previously shown that AhR activation modulated the IFN-γ production in Mφ upon viral infection and autoimmune disease both ex vivo and in vivo." (PMID 37287978, 2023). "Finally, the development of a delivery system for AHR agonists and autoantigens will be urgent because successful delivery of such contents to DCs and other myeloid cells and subsequent establishment of tolerance will increase the use of therapeutic vaccines for autoimmune diseases." (PMID 37394584, 2023). "Several autoimmune diseases, including systemic lupus erythematosus (SLE), have been connected to AhR in previous studies." (PMID 36110860, 2022). "AhR activation is reduced in diseases including IBD, liver disease, metabolic syndrome, autoimmune disease, and cancer, suggesting that alteration in Trp metabolism or indole production my contribute to AhR dysfunction." (PMID 33916690, 2021). "Our findings suggest that GLK-induced AhR–ROR-γt complex is a biomarker and therapeutic target for IL-17A–mediated autoimmune disease." (PMID 31318609, 2019). "The AHR modulates T cell differentiation and effector function in vitro and in experimental autoimmune encephalomyelitis (EAE), a murine model of autoimmune disease." (PMID 30143013, 2018). "Tr1 cells are regulated by AHR and characterized as FOXP3−CD4+ T cells that require IL-27, produce IL-10, and have been shown to prevent autoimmune disease." (PMID 30574142, 2018). "This review summarizes the most current findings regarding the functions of AHR and IDO in immune cells as they relate to the pathogenesis of autoimmune diseases in response to various stimuli." (PMID 25400638, 2014). "Recent findings have elucidated the critical link between AHR and indoleamine 2,3-dioxygenase (IDO) in the development of regulatory T cells and Th17 cells, which are key factors in a variety of human autoimmune diseases." (PMID 25400638, 2014). "We also discuss the potential link between AHR and IDO/tryptophan metabolites, and the involvement of several novel related factors (such as microRNA) in the development of autoimmune diseases." (PMID 25400638, 2014). "Given the opposing effects of ITE in autoimmune diseases and cancer models, we hypothesized that ITE might competitively block other ligands by binding to AHR with high affinity." (PMID 40283908, 2025).
autoimmune disease (continued). "Additionally, aryl hydrocarbon receptor regulates the differentiation and balance of CD4+ T helper 1, 2, 17, follicular, and regulatory immune cells, which are central in development of autoimmune diseases like SLE and DLE." (PMID 39552756, 2024). "AhR can instigate the production of Th17 cells and Treg cells based on the concentration of TCDD in experimental autoimmune encephalomyelitis (EAE), suggesting that the distribution between Th17 and Treg cells poses an important role in autoimmune disease." (PMID 38518996, 2024). "Furthermore, non-photoactivated VP also inhibited IL-17A production by the AhR-RORγt complex by targeting GLK, which is suggestive of a potential therapeutic effect against Th17-mediated autoimmune diseases." (PMID 33178014, 2020). "The AhR can induce Treg cells and Th17 cells based on the TCDD concentration in EAE, suggesting that the balance between Treg cells and Th17 cells has a key role in autoimmune disease." (PMID 29487603, 2018). "Given the increased interest in the role of the AhR in orchestrating Th17 cell responses, it is not surprising that it is being considered currently as a therapeutic target in a range of Th17 autoimmune diseases." (PMID 25203682, 2014). "In autoimmune diseases such as rheumatoid arthritis (RA), systemic lupus erythematosus (SLE), multiple sclerosis (MS), and membranous nephropathy (MN), dysregulation of this axis is characterized by excessive HIF-1α signaling and relative insufficiency of the IDO1/AhR pathway." (PMID 41869303, 2026). "This suggests that AhR could be an important factor in the negative feedback mechanism in IFN-γ–mediated autoimmune disorders." (PMID 40162433, 2025). "Based on the immunosuppressive effects of AhR ligands on autoimmune diseases, such as EAE, it would be reasonable to propound that activation of AhR in the tumor microenvironment corresponds to increased numbers of Treg cells, which could also account for the tumor-promoting properties of TCDD." (PMID 38518996, 2024). "Mechanistically, there is evidence that activation of the aryl hydrocarbon receptor (AhR) upon TCDD binding leads to BZLF1 gene expression and EBV reactivation in both B cells and salivary epithelial cells, which shows potential consequences in autoimmune diseases and cancer." (PMID 34193233, 2021). "Although the AHR is unlikely to be the whole story, it may be a start to identifying mechanisms to alleviate symptoms of autoimmune disease as well as prevent disease all together." (PMID 30574142, 2018). "Thus, with regards to TH17-mediated autoimmune diseases, the lack of AHR would impair the disease development." (PMID 30425241, 2018). "Together, these findings demonstrate that AhR signaling promotes Treg generation concurrent with enhanced Lkb1-mediated FAO, suggesting that AhR agonists might be leveraged therapeutically as potent inducers of Treg cells to prevent and treat autoimmune disease." (PMID 39007133, 2024).
inflammatory bowel disease (88 papers, 2013 to 2026). A spectrum of small and large bowel inflammatory diseases of unknown etiology. "In murine models of inflammatory bowel disease, a deficiency in AhR signaling increased disease progression, inflammatory responses, and epithelial damage." (PMID 40856156, 2025). "Nevertheless, AHR-deficient eosinophils increased pathways relating to inflammatory bowel disease, TNFR2, and NF-κB pathways." (PMID 35238865, 2022). "The crucial importance of the AhR pathway in the regulation of the intestinal immune system has been demonstrated by genome-wide association studies that have identified the AHR gene as a susceptibility locus in inflammatory bowel diseases." (PMID 33451129, 2021). "In this context, genome-wide association studies have identified AHR as a susceptibility locus in inflammatory bowel diseases." (PMID 31683543, 2019). "The ligand-dependent nature of AHR activity may provide an opportunity to interfere with disorders such as cancer and inflammatory bowel diseases which are caused by dysregulation in intestinal tissue renewal." (PMID 40353141, 2025). "Previous studies have demonstrated that microbiota-derived tryptophan metabolites, such as indole, which are ligands for the aryl hydrocarbon receptor (AhR), have a major role in intestinal homeostasis and have been implicated in the pathogenesis of metabolic syndrome and inflammatory bowel disease." (PMID 31121956, 2019). "AhR was recently suspected to be implicated in inflammatory bowel disease." (PMID 24236236, 2013). "Furthermore, it has been shown that AHR plays a crucial role in keeping the digestive epithelium healthy, and that the lack of activation of AHR by bacterial tryptophan metabolites is associated with an aggravation of inflammatory bowel diseases." (PMID 35324718, 2022). "AhR activation is associated with multiple diseases such as inflammatory bowel disease (IBD), type 2 diabetes, and central nervous system (CNS)-related disorders." (PMID 35050132, 2021). "Malfunction of AhR signaling and Trp metabolism within the microbiome metabolome was recently linked to human inflammatory bowel disease (IBD), an autoimmune disorder related to an aberrant immune response associated with the T cell compartment." (PMID 33086747, 2020). "Since 2010, disruptions in AHR signaling have been shown to be involved in the development of diseases such as inflammatory bowel disease (IBD) and atopic dermatitis (AD)." (PMID 41540003, 2026). "Keywords included ‘inflammatory bowel disease’, ‘colorectal cancer’, ‘AhR’, ‘aryl hydrocarbon receptor’, ‘GPR35’, ‘cytochrome P450’, ‘nutraceuticals’, ‘probiotics’, and ‘superfoods’." (PMID 41009721, 2025). "This study discovered a positive relationship between the AhR-related pathway and Dubosiella, suggesting that the AhR pathway can be a promising target for treating inflammatory bowel disease." (PMID 40806121, 2025). "Ganoderic Acid A (GAA) can potentially ameliorate inflammatory bowel disease by modulating the intestinal flora and enhancing AhR activity, which in turn promotes IL-22 production and improves intestinal barrier function." (PMID 41019044, 2025). "Here, we investigated the role of AhR in modulating the functions of macrophages in inflammatory bowel disease pathogenesis." (PMID 39113799, 2024). "AHR expression is defective in the inflamed gut of patients with inflammatory bowel diseases (IBD), where decreased AHR signaling is supposed to contribute to amplifying the gut tissue’s destructive immune–inflammatory responses." (PMID 38674118, 2024). "It has been demonstrated that ALD, metabolic syndrome, and inflammatory bowel disease can all be improved by AhR activation." (PMID 38596381, 2024). "Genetic knockout of P2rx1 has been reported to be beneficial to inflammatory bowel disease by aryl hydrocarbon receptor (AhR)/IL-22 axis involved in microbiota metabolites." (PMID 37046119, 2023).
inflammatory bowel disease (continued). "For example, activation of AHR in the gut can be beneficial for the treatment of inflammatory bowel disease." (PMID 37894798, 2023). "With increasing knowledge of the physiological and pathophysiological roles of AhR, attempts to target AhR have emerged, including the therapy of cancer, inflammatory bowel disease, and atopic dermatitis." (PMID 37169746, 2023). "Multiple AhR agonists have been tested in inflammatory bowel disease clinical trials that were originally derived from traditional medicines." (PMID 35626744, 2022). "AhR activation by microbial Trp metabolism is involved in the pathogenesis of metabolic syndrome, inflammatory bowel disease, celiac disease, alcohol-induced liver injury, candidiasis, and EAE." (PMID 35727038, 2022). "The AhR has been shown to play a protective role within the gut by mediating immune homeostasis and maintaining barrier integrity, and several therapeutic modality approaches have been developed to target the AhR pathway to combat inflammatory bowel disease." (PMID 35626744, 2022). "The AHR plays a relevant role in many immune and inflammatory processes, such as multiple sclerosis, rheumatoid arthritis, asthma, inflammatory bowel disease (IBD), chloracne, AD, and PS." (PMID 34831399, 2021). "Treatment of inflammatory bowel diseases with the AhR agonist, diet and balanced gut microbiota promotes Treg differentiation and attenuates inflammation." (PMID 32899152, 2020). "Enhanced AhR activity is associated with disease in autoimmune patients and preclinical models of disease, and AhR agonists have been shown to inhibit inflammation in models of inflammatory bowel disease, systemic lupus erythematosus, and rheumatoid arthritis." (PMID 32973768, 2020). "In T helper type 17 (Th17) cells, ligation of the aryl hydrocarbon receptor to bilirubin results in abrogation of inflammatory bowel disease." (PMID 31402920, 2019). "That cluster, induced by the activation of AhR in inflammatory bowel disease, was able to promote an inflammatory response by inducing the Th17 response and suppressing IL-10 production." (PMID 30648118, 2018). "For example, AHR activation is protective in inflammatory bowel disease, partly due to increased IL10 expression." (PMID 30184180, 2018). "For example, IL10 expression can be induced using AHR agonists as a protective mechanism in inflammatory bowel disease, or repressed by an endogenous VDR agonist (calcitriol) during pregnancy to enhance responses to microbial infections." (PMID 30184180, 2018). "In intestinal epithelial cells, AHR activation improves intestinal barrier function by maintaining tight junction proteins (ZO-1, Occludin, and Claudin-1) and alleviates inflammation by inhibiting NF-κB, thereby improving inflammatory bowel disease." (PMID 41513604, 2026). "I3C and its condensation products have potential effects in treating inflammatory bowel diseases by modulating the differentiation and function of T cells (Treg cells) through AhR activation, while reducing the number of helper T cells (Th cells) to alleviate intestinal inflammation." (PMID 39944639, 2025). "The advancement of AHR-targeted therapies derived from bacterial products may offer a significant alternative strategy for the management of inflammatory bowel disease (IBD)." (PMID 39575260, 2024). "Given that chronic intestinal inflammation, as seen in inflammatory bowel diseases, increases the risk of CRC, AhR’s role in modulating inflammation may be key to its tumor-suppressing function." (PMID 39767818, 2024). "Suppression of CMA might increase the AHR protein levels in the gut and thereby elicit a synergistic effect of AHR activation when used in combination with an AHR agonist—an interesting regimen for the treatment of inflammatory bowel disease." (PMID 37894798, 2023).